GPR68 (G protein-coupled receptor 68)
Diseases named in the same sentence as GPR68 in open-access papers (continued):
Sharing a sentence is not in itself a finding about the gene and the disease.
airway hyperresponsiveness (4 papers, 2013 to 2024). "This was associated with a reduced ability of CD11c+ dendritic cells from GPR68−/− mice to transfer airway hyperresponsiveness to WT mice." (PMID 36611126, 2023). "Similarly, Sulazepam was found to activate Gs signaling in HEK293 cells as well and has been demonstrated to prevent allergen-induced airway hyperresponsiveness through GPR68." (PMID 39336742, 2024). "Interestingly, genetic deletion of GPR68 in a dust-mite-induced airway hyperresponsiveness (AHR) mouse model did not protect against allergen-induced lung inflammation." (PMID 39336742, 2024).
cervical squamous cell carcinoma (4 papers, 2019 to 2022). A squamous cell carcinoma arising from the cervical epithelium. "GPR68 is overexpressed in numerous tumor types, including pancreatic ductal adenocarcinoma (PDAC), cervical squamous cell carcinoma, endocervical adenocarcinoma (CESC), breast adenocarcinoma, and ovarian cancer." (PMID 33746610, 2021). "Pronounced GPR68 expression associated with higher IRS values was seen especially in a subpopulation of neuroendocrine tumours, pheochromocytomas, adenocarcinomas of the cervix (in contrast to squamous cell carcinomas of the cervix, which were negative) and endometrial cancer." (PMID 31652823, 2019). "GPR68 is substantially expressed (>5 transcripts per million [TPM]) in several tumor types, notably in head and neck squamous carcinoma (HNSC), cervical squamous cell carcinoma (CESC), pancreatic and lung cancers among others." (PMID 30696114, 2019).
atherosclerosis (3 papers, 2025 to 2026). A disease characterized by the build-up of fatty material and calcium deposition in the arterial wall resulting in partial or complete occlusion of the arterial lumen. "The negative correlation with these biomarkers suggests that higher levels of DHX36 and GPR68 may be associated with reduced monocyte activity or recruitment, which could impact the inflammatory processes underlying atherosclerosis." (PMID 41614904, 2026). "The enrichment analysis identified several critical pathways associated with the biomarkers DHX36 and GPR68, which may play pivotal roles in the pathogenesis of atherosclerosis." (PMID 41614904, 2026). "Collectively, these pathways underscore the multifaceted roles of DHX36 and GPR68 in atherosclerosis and warrant further investigation into their potential as therapeutic targets." (PMID 41614904, 2026). "This leads us to hypothesize that CD8+ T cells may further inhibit the progression of atherosclerosis through mechanisms involving DHX36 or GPR68." (PMID 41614904, 2026). "Furthermore, the responsiveness of GPR68 to mechanical and chemical stimuli suggests that it may influence the onset and progression of atherosclerosis through multiple pathways under various pathological conditions." (PMID 41614904, 2026).
hepatocellular carcinoma (3 papers, 2019 to 2025). A malignant tumor that arises from hepatocytes. "Transcriptome analysis revealed that Conophylline (CnP), a vinca alkaloid derived from leaves, strongly inhibited GPR68 in cancer-associated fibroblasts (CAFs) and consequently inhibited the hepatocellular carcinoma (HCC)-promoting effect of CAFs." (PMID 38505262, 2024).
myelodysplastic syndrome (3 papers, 2019 to 2022). A clonal hematopoietic disorder characterized by dysplasia and ineffective hematopoiesis in one or more of the hematopoietic cell lines. "Promoter region analysis and chromatin immunoprecipitation-sequencing (ChiP-seq) revealed that GPR68 contained binding peaks for Ikaros family zinc finger 1 (IKZF1); IKZF1 functions as a transcriptional repressor of GPR68 in a myelodysplastic syndrome (MDS) cell line." (PMID 30696114, 2019).
osteosarcoma (3 papers, 2013 to 2021). A usually aggressive malignant bone-forming mesenchymal neoplasm, predominantly affecting adolescents and young adults. "And many of them, such as ZNRD1, GPR68, CAT, FUT3, ANPEP, CDK1, and hsa-miR-543, might be key genes related to osteosarcoma chemoresistance." (PMID 29850522, 2018). "Among them, hsa-miR-543, as well as ZNRD1, GPR68, CAT, FUT3, ANPEP, and CDK1 genes, were proposed as crucial players in osteosarcoma chemoresistance, and hence they could represent potential therapeutic targets for osteosarcoma." (PMID 35011442, 2021).
pheochromocytoma (3 papers, 2019 to 2025). "Further investigations in other (neuro)endocrine tumour entities with a high prevalence of GPR68, such as pheochromocytomas, paragangliomas, and medullary thyroid carcinomas, but also with cervical adenocarcinomas and endometrial cancer will be of interest in this respect." (PMID 31652823, 2019). "GPR68 was also expressed in neuroendocrine tumours, where it may be a positive prognostic factor, in pheochromocytomas, cervical adenocarcinomas, and endometrial cancer, as well as in paragangliomas, medullary thyroid carcinomas, gastrointestinal stromal tumours, and pancreatic adenocarcinomas." (PMID 31652823, 2019).
squamous cell carcinoma (3 papers, 2019 to 2023). A carcinoma arising from squamous epithelial cells. "4NQO treatment resulted in 45 percent of GPR68−/− mice developing severe dysplasia or squamous cell carcinoma compared to only 10.5 percent of GPR68+/+ mice." (PMID 36611126, 2023).
Stroke (3 papers, 2024 to 2026). Sudden impairment of blood flow to a part of the brain due to occlusion or rupture of an artery to the brain. "In the stroke brain, overexpression of GPR68 exerted neuroprotection and was able to alleviate the neuronal damage via inhibiting the protein kinase C (PKC) activation." (PMID 41164084, 2025). "We detail the molecular logic of this axis-from GPR68's sensing of pathological acidosis (pH ≤ 6.4) and shear stress to NINJ1's oligomerization and DAMP release-and explore its potential role in unifying the pathophysiology of diverse disorders like TBI, stroke, MS, and AD." (PMID 41969524, 2026).
cardiac ischemia (2 papers, 2018 to 2021). "Despite both GPR4 and GPR68 having apparent roles in the pathophysiology of cardiac ischemia, it may be that they have opposing roles in cardiomyocytes in the presence of ischemic insult." (PMID 29367584, 2018). "It is interesting to note that we have not observed upregulation of GPR68 when myocardial ischemia and acidosis has been corrected by reperfusion (I/R; data not shown)." (PMID 29367584, 2018).
Crohn disease (2 papers, 2019 to 2023). A gastrointestinal disorder characterized by chronic inflammation involving all layers of the intestinal wall, noncaseating granulomas affecting the intestinal wall and regional lymph nodes, and transmural fibrosis. "Hypoxia has been reported to contribute to increased expression of GPR68 by intestinal macrophages and colonic tissue and further to this, elevated GPR68 mRNA was observed in intestinal mucosa from ulcerative colitis and Crohn's disease patients." (PMID 31544616, 2019).
endothelial dysfunction (2 papers, 2024 to 2025). In vascular diseases, endothelial dysfunction is a systemic pathological state of the endothelium (the inner lining of blood vessels) and can be broadly defined as an imbalance between vasodilating and vasoconstricting substances produced by (or acting on) the endothelium. "The present study reports for the first time the role of GPR68 in propagation of endothelial dysfunction and lung injury caused by bacteria-derived pathogens." (PMID 41193514, 2025). "Although GPR68 has been implicated in flow-induced, EC-dependent vasodilation, its role in endothelial dysfunction caused by ARDS-related insults remains unknown." (PMID 41193514, 2025). "Collectively, these findings strongly indicate that acidosis activates pH sensor GPR68 in EC, which mediates acidosis-induced endothelial dysfunction." (PMID 39768215, 2024). "In support of our notion, an essential role of GPR68 in acidosis-triggered endothelial dysfunction was further verified by the observations that Ogerin, a synthetic GPR68 activator, augmented acidic pH-induced endothelial inflammation." (PMID 39768215, 2024). "We also evaluated the effectiveness of our newly developed GPR68 small molecular inhibitor OGM-8345 in rescuing acidosis-driven endothelial dysfunction." (PMID 39768215, 2024). "Moreover, assessment of pharmacological inhibitors of GPR68 and GPR4 on acidic pH-caused endothelial dysfunction further assisted to delineate the involvement of these receptors." (PMID 39768215, 2024). "Herein, we present the evidence that GPR68 is not only the critical mediator of acidosis-induced lung endothelial dysfunction but also drives synergistic pro-inflammatory effects of acidic pH and LPS leading to severe endothelial dysfunction." (PMID 39768215, 2024). "However, a precise role of GPR68 in mediating acidosis or inflammatory agonist-induced endothelial dysfunction remains unknown." (PMID 39768215, 2024). "In this study, we analyzed the role of GPR68 in mediating acidosis-induced permeability and inflammation in primary cultures of human lung ECs and evaluated the synergistic effects of acidification and bacterial lipopolysaccharide (LPS) in exacerbating endothelial dysfunction." (PMID 39768215, 2024). "As our results suggested that GPR68 activation enhances acidosis-induced endothelial barrier disruption and inflammation, we next tested the hypothesis that GPR68 inhibition rescues acidic pH-derived endothelial dysfunction." (PMID 39768215, 2024). "Most importantly, the GPR68-targeting small molecule inhibitor OGM-8345 exerts robust protection against acidosis-induced endothelial dysfunction, suggesting that it could be considered as a potential therapeutic drug candidate to restore endothelial function and treat associated lung injuries." (PMID 39768215, 2024).
experimental autoimmune encephalomyelitis (2 papers, 2016 to 2023). An autoimmune demyelinating disease of the central nervous system that is produced experimentally in animals by the injection of homogenized brain or spinal cord in Freund's adjuvant. "A murine model of multiple sclerosis, experimental autoimmune encephalomyelitis, demonstrated a pathogenic role for GPR68 in promoting disease." (PMID 36611126, 2023).
glioma (2 papers, 2024). A benign or malignant brain and spinal cord tumor that arises from glial cells (astrocytes, oligodendrocytes, ependymal cells). "To confirm that the effect of OGM on glioma cells is due to GPR68 inhibition, we knocked down GPR68 using siRNA in U87 and U138 cells." (PMID 38291540, 2024). "Our analysis of glioma datasets downloaded from The Cancer Genome Atlas (TCGA) unveiled significant differences in expression patterns between normal and tumor tissues, specifically an upregulation of GPR65, and a downregulation of GPR68." (PMID 38576043, 2024).
head and neck cancer (2 papers, 2020 to 2023). A primary or metastatic malignant neoplasm affecting the head and neck. "Previously, a gene expression analysis revealed that GPR68 is upregulated in head and neck cancer and associated with cisplatin-resistance, hypoxia, angiogenesis and TGF-β expression." (PMID 36611126, 2023). "RNA knockdown studies revealed that GPR68 did not directly affect the survival and growth of head and neck cancer cell lines." (PMID 36611126, 2023).
head and neck squamous cell carcinoma (2 papers, 2023 to 2025). A squamous cell carcinoma that arises from any of the following anatomic sites: lip and oral cavity, nasal cavity, paranasal sinuses, pharynx, larynx, and salivary glands. "Through clinical data analysis, GPR68 was found to be highly expressed in head-and-neck squamous cell carcinoma and to correlate with disease progression and patient survival." (PMID 41190345, 2025). "Therefore, GPR68 may be a potential therapeutic target and prognostic marker for the management of head and neck squamous cell carcinoma." (PMID 41190345, 2025).
heart failure (2 papers, 2021 to 2023). Inability of the heart to pump blood at an adequate rate to meet tissue metabolic requirements. "Therefore, we further focused on Gpr68 as a CLOCK-dependent 5/6Nx-induced gene and investigated its function in CKD-induced heart failure." (PMID 33986294, 2021).
Hypertension (2 papers, 2021 to 2025). The presence of chronic increased pressure in the systemic arterial system. "Similarly to WT mice, Gpr68−/− male mice were susceptible to Ang II-induced hypertension." (PMID 40560060, 2025). "This study demonstrates that the pH-sensing receptor GPR68 partially mediates how dietary fibre lowers BP in a pre-clinical model of hypertension." (PMID 40560060, 2025). "Here, we aimed to investigate whether GPR68 confers the BP-lowering effects of a high-fibre diet in hypertension by regulating inflammatory responses." (PMID 40560060, 2025). "We demonstrate that pH-sensing receptor GPR68 may offer a new approach for leveraging the BP-lowering effects of dietary fibre in hypertension, likely through immune-independent pathways." (PMID 40560060, 2025). "As GPR68 is particularly enriched in immune cells, we explored whether the immune system mediates the mechanistic link between GPR68 and dietary fibre in hypertension." (PMID 40560060, 2025). "Targeting the pH-sensing receptor GPR68 may offer a new approach for leveraging the BP-lowering effects of dietary fibre in hypertension." (PMID 40560060, 2025). "Therefore, in this study, our primary aim was to determine whether GPR68 confers the BP protective effects of dietary fibre in a pre-clinical model of hypertension." (PMID 40560060, 2025). "WT female mice did not develop higher BP when challenged with Ang II, and GPR68 did not sensitise female mice to Ang II-induced hypertension." (PMID 40560060, 2025). "However, there was no improvement of the common features of CKD in GPR68-downregulated 5/6Nx wild-type mice, such as hypertension or increased serum levels of angiotensin II, aldosterone, or urea nitrogen." (PMID 33986294, 2021). "Consequently, the monocytic expression of Gpr68 was not induced in 5/6Nx Clk/Clk mice and they exhibited attenuation of cardiac inflammation and fibrosis, although they also had high blood pressure and RAAS activation." (PMID 33986294, 2021).
ischemic stroke (2 papers, 2022 to 2024). A stroke disorder caused by obstruction of blood flow to the brain, due to thrombotic (local blood clot formation) or embolic (due to a blood clot or other material traveling from another site) event. "GPR68, known to protect neurons from death in ischemic stroke, suggests a potential mechanism for cancer cells to resist oxidative stress." (PMID 38291540, 2024). "The induction of Siglec-E expression in the brain following ischemic stroke was first reported in a recent transcriptome screening study and appeared dependent on GPR68, a neuronal metabotropic proton receptor that mediates neuroprotection in acidotic and ischemic conditions." (PMID 35858866, 2022).
liver cancer (2 papers, 2019 to 2025). An epithelial or non-epithelial malignant neoplasm that arises from the liver. "However, few studies have investigated the relationships among P2RY4, GPR68, and liver cancer, and elucidating these relationships could be a direction for future research." (PMID 31236404, 2019).
lung carcinoma (2 papers, 2019 to 2022). "Besides the tumour cells, especially in cases of lung cancer but also in some cases of other tumour entities such as prostate adenocarcinoma or lymphoma, the tumour capillaries were also strongly GPR68-positive." (PMID 31652823, 2019).
lung disease (2 papers, 2022 to 2024). "This work adds to the understanding of Gαs coupled GPCRs in fibrotic lung disease, the ability to harness the pH sensing properties of GPR68, and conserved mechanisms of fibrosis across different organ systems." (PMID 35901086, 2022). "Thus, GPR68 may confer differential roles through biased signaling, and the exact role of GPR68 in the context of lung disease remains to be elucidated." (PMID 39336742, 2024).
myocardial infarction (2 papers, 2021 to 2026). Gross necrosis of the myocardium, as a result of interruption of the blood supply to the area, as in coronary thrombosis. "Future studies incorporating additional models, such as myocardial infarction or ischemia–reperfusion models, would provide complementary insights into the broader spectrum of CHD pathology and further validate the roles of DHX36 and GPR68 across different disease contexts." (PMID 41614904, 2026).
neuroendocrine tumors (2 papers, 2019 to 2023). "If only bronchopulmonary neuroendocrine tumours were considered, a positive association was detected between GPR68 expression and patient overall survival (rsp = 0.234, p = 0.035) and a negative correlation with levels of the proliferation marker Ki-67 (rsp = –0.222, p = 0.043)." (PMID 31652823, 2019). "Based on these findings, we expanded the number of neuroendocrine tumours studied and ultimately evaluated a broad panel of bronchopulmonary and gastroenteropancreatic neuroendocrine neoplasms of different origins for GPR68 expression." (PMID 31652823, 2019). "Overall, regarding the percentage of signal-positive tumours (IRS ≥ 3) and the extent of expression, GPR68 was most prominently expressed in neuroendocrine tumours from the pancreas, followed by those from the rectum or gut and typical carcinoids of the lung." (PMID 31652823, 2019). "Together, our findings indicate that in neuroendocrine tumours, GPR68 may act as a tumour suppressor." (PMID 31652823, 2019). "Additionally, in gastroenteropancreatic neuroendocrine neoplasms, a tendency towards lower GPR68 levels was observed in the metastases as compared to the primary tumours (primary tumours: 1.833 ± 0.241, metastases: 1.286 ± 0.252; Mann–Whitney test: p = 0.089)." (PMID 31652823, 2019). "Therefore, it was expected that the most robust GPR68 expression in all cell lines tested was observed in the neuroendocrine tumour cell line BON-1." (PMID 31652823, 2019). "Among the large panel of neuroendocrine tumours investigated, differences in GPR68 expression were observed with respect to the localisation and malignancy of the tumour entities, with higher IRS values in tumours of the pancreas, rectum, or gut compared to those from other sites." (PMID 31652823, 2019). "Only in a few cases of pancreatic (likely glucagon-producing) neuroendocrine tumours with exceptionally high expression GPR68 may be of some interest in this respect." (PMID 31652823, 2019). "Thus, GPR68 is clearly of no relevance as a diagnostic or therapeutic target in all these tumour entities, including bronchopulmonary and gastroenteropancreatic neuroendocrine tumours." (PMID 31652823, 2019). "If only gastroenteropancreatic neuroendocrine tumours were included in the analysis, significantly higher GPR68 levels were again noted in patients without lymph node metastases (without lymph node metastases: 2.473 ± 0.512; with lymph node metastases: 1.449 ± 0.238; Mann–Whitney test: p = 0.012)." (PMID 31652823, 2019).
osteoarthritis (2 papers, 2025 to 2026). A noninflammatory degenerative joint disease occurring chiefly in older persons, characterized by degeneration of the articular cartilage, hypertrophy of bone at the margins and changes in the synovial membrane. "Moreover, GPR68 exhibits notable elevation in multiple aging-related diseases, such as cancer, osteoarthritis (OA), and others." (PMID 41190345, 2025).
renal fibrosis (2 papers, 2024 to 2025). A final common manifestation of a wide variety of chronic kidney diseases characterized by glomerulosclerosis and tubulointerstitial fibrosis. "However, GPR68 deficiency resulted in smaller renal weights but no associated change in overall renal fibrosis." (PMID 40560060, 2025). "In CKD mouse models lacking monocyte-specific ARNTL, GPR68 expression in monocytes was reduced, leading to decreased cardiac damage and fibrosis despite no improvement in renal excretory capacity or renal fibrosis and increased angiotensin II production." (PMID 39684718, 2024).